MSLN (mesothelin)
Diseases named in the same sentence as MSLN in open-access papers (continued):
Sharing a sentence is not in itself a finding about the gene and the disease.
tumor (continued). "In this study, the PET imaging using the 89Zr-labeled anti-MSLN-scFv clone (H1a050) with high reactivity to MSLN-expressing cancer cells clearly displayed the MSLN-positive tumor derived from NCI-N87 cancer cells but not the MSLN-negative tumor derived from PANC-1 cells." (PMID 33670777, 2021). "Since mesothelin is overexpressed in several cancers and is immunogenic, the protein could be exploited as a tumor marker, unfortunately, it is not a specific antigen for cancer." (PMID 34926461, 2021). "Therefore, MSLN expression was analyzed in more than 15,000 tumor tissue samples from 122 different tumor types and subtypes, as well as 76 non-neoplastic tissue categories, by immunohistochemistry (IHC) in a tissue microarray (TMA) format in this study." (PMID 33917081, 2021). "To determine whether MSLN scFv-LGA-PEI NPs with NAs could target MSLN-expressing cancer tumor tissues in vivo, we orthotopically implanted the PDX line (PAN3) into the pancreas of an NSG mouse (NOD scid gamma mouse) for 3 weeks, when the tumor was established." (PMID 34577541, 2021). "Interestingly, MSLN-CAR NK cells could lead to complete response in the PDX tumor model, indicating their potent tumor elimination capability." (PMID 34671203, 2021). "Hence, this study concluded that the newly discovered anti-MSLN-scFv enabled clear visualization of MSLN-expressed tumors via PET imaging at just 3 hr post-injection, suggesting that it may be a useful candidate for tumor imaging." (PMID 33670777, 2021). "Achieving more accurate and convincing MSLN CAR cell-mediated targeting is the primary goal of several research groups but requires the tackling of various challenges such as production, infiltration into solid tumors, and overcoming the immunosuppressive effects of the tumor microenvironment." (PMID 34943898, 2021). "This therapy could be used to direct phagocytic anti-tumor immunity against tumor antigen expressing cells (e.g. human epidermal growth factor receptor (HER2), mesothelin) or use alongside CAR T cell therapies to improve T cell penetration into the sarcoma through ECM breakdown." (PMID 33381449, 2020). "We could not detect MSLN in the G12V tumor proteome, while it was highly expressed in the WT tumor (MSLN↑WT; 22 peptides and 118 PSM) which is in good agreement with the transcriptomic data." (PMID 31805664, 2019). "After an overnight incubation, significant cell-mediated cytotoxicity was observed in dCAR-T cells co-cultured with cognate tumor cells expressing both CEA and MSLN, with approximately 80% of target cell apoptosis which was similar to that of conventional CAR-T cells (CEA-CAR T or MSLN-CAR T)." (PMID 30103775, 2018). "Furthermore, MVA virus (with and without mesothelin expression) was able to replicate in and kill Panc02 tumor cells grown in vitro, suggesting that it would be an effective oncolytic virus in vivo." (PMID 29474384, 2018). "The studies reported here highlight an important property of anti-mesothelin mAb amatuximab as compared to anti-Lewis-Y mAb B3 for the Ag-mediated targeting of A431/H9 tumor overexpressing both a shed Ag, mesothelin, and a nonshed Ag, Lewis-Y, in a mouse model." (PMID 29720923, 2018). "Tumors generated from all MPM cultures were strongly positive for calretinin, confirming that the in-vitro growth did not modify the epithelioid subtype phenotype of the tumor of origin, while the expression of D2-40, WT-1, and mesothelin supported their mesothelial origin." (PMID 28545562, 2017). "Besides, mesothelin-specific CAR-T cells induced bystander killing of mesothelin-negative tumor cells." (PMID 28356156, 2017).
tumor (continued). "Overexpression of mesothelin inhibited tumor formation in vivo, but not growth in vitro." (PMID 26931187, 2016). "This may seem a rather low uptake, but a recent study using an 111In-labeled anti-ERC/mesothelin mouse monoclonal IgG2a did not exceed 5.8%ID/g in the tumor at any time point of 24, 48 or 96 h." (PMID 26536664, 2015). "An anti-mesothelin ADC, Anetumab ravtansine, which is a fully human anti-mesothelin antibody conjugated to an average of 3.2 molecules of the cytotoxic maytansine drug DM4, was reported to exhibit bystander activity in tumor xenograft models." (PMID 25339341, 2015). "The relationship between efficacy and mesothelin expression is unclear, since apparent tumor regression could not be observed in this study." (PMID 25502863, 2015). "Notably, in mice treated with gemcitabine, levels of gemcitabine that did not significantly affect tumor size did not affect the serum level of N-ERC/mesothelin." (PMID 25347530, 2014). "Additionally, studies in nude mice with mesothelin-expressing tumor xenografts reveal enhanced therapeutic responses when taxon, or other cancer drugs, are administered in combination with SS1P, a high-affinity immunotoxin that targets mesothelin." (PMID 24990559, 2014). "The attachment of tumor-released mesothelin to a GPI anchor was shown using a novel ELISA assay that detects soluble molecules bearing both a mesothelin epitope and GPI core glycan moieties, as well as by lipid profiling of mesothelin immunoprecipitated from tumor cell conditioned media." (PMID 22163010, 2011). "Mesothelin is frequently expressed on RM and MM, but despite earlier claims that its expression is limited to cells of mesothelial lineage, has been shown to be expressed in several tumor types, including non-mucinous ovarian, lung and pancreatic AC." (PMID 19662202, 2007). "Moreover, it can exert a bystander effect on adjacent tumor cells that do not express MSLN." (PMID 40362535, 2025). "However, even CAR-T cell therapies face many obstacles, including off-tumor toxicity, limited trafficking, and immunosuppressive TME, that limit their clinical efficacy, highlighting the need for a better understanding of MSLN functional roles in tumor progression and TME remodeling." (PMID 41335396, 2025). "Interestingly, genetic knockdown of MSLN significantly reversed EMT and attenuated stem cell properties, in addition to inhibiting tumor growth and metastasis; ectopic overexpression of MSLN induced the malignant phenotype of non-tumoral cells, supporting its role as an oncogene." (PMID 37901248, 2023). "Hence, SS1P was not antagonized by shed mesothelin and could readily bind membrane mesothelin and kill tumor cells." (PMID 34976821, 2021). "However, the combination of anti-mesothelin CAR-T cells (CARMSLNz T) with dPD1z T or CARPD-L1z T cells did not repress tumor growth synergistically in PDX, as CARMSLNz T cells upregulated PD-L1 expression upon activation and were subsequently attacked by dPD1z T or CARPD-L1z T cells." (PMID 32514352, 2020). "Survival analyses revealed the association between mesothelin expression and poor overall survival, whereas lack of PTEN protein expression associated with lower progression-free survival with anti-EGFR-based therapy in the first-line setting for patients with RAS wild-type tumour." (PMID 31537838, 2019). "Although MSLN appears to be non-essential in normal tissues since MSLN knockout mice exhibit no detectable malfunction in tissue development, reproduction, and blood cell count, clinical studies have shown that high MSLN expression correlates with tumor aggressiveness in many solid tumors." (PMID 28288645, 2017). "MSLN is selectively overexpressed in a majority of TNBC tumors while largely absent in normal tissues, establishing it as a safe and tumor-specific target." (PMID 41348261, 2025).
tumor (continued). "A CAR T cell product using mRNA electroporation that transiently expressed the anti-MSLN CAR on T cells, exhibited a safety profile in a phase I trial; however, no tumor responses were registered in patients with MM." (PMID 38893092, 2024). "While T-BsAb targeting EGFR and mesothelin failed to significantly reduce tumor growth, HER2-targeted T-BsAbs displayed potent anti-tumor activity, eliminating tumors derived from two different cell lines with durable responses." (PMID 39139449, 2024). "The biomarkers identified in the T3 subtype include MSLN and CD117 (KIT), which have been reported in TC and other advanced tumor cells, and CCL20 which has not been reported in TC." (PMID 39258580, 2024). "In a recent study, mesothelin, mucin 4 (MUC4), annexin A10 (ANXA10), and glypican 1 (GPC-1) were observed to be selectively expressed in the tumor when compared to non-neoplastic pancreatic ducts and acini." (PMID 39062863, 2024). "Unlike mesothelin and CA125, which have a broader expression in normal tissues, the differential expression of FRα in tumors compared to normal tissues enhances tumor selectivity for drugs." (PMID 39526448, 2024). "Similarly, in another trial of six PDAC patients, intravenous delivery of anti-mesothelin CAR T-cells resulted in stable disease, with progression-free survival (PFS) times of 3.8 and 5.4 months in two patients, respectively, and no adverse complications associated with off-tumor toxicities." (PMID 37020537, 2023). "CAR T cells failed to inhibit tumour growth in the OV0276 model, which was an MSLN-negative PDX model." (PMID 36166071, 2023). "The similar tumour and organs biodistributions obtained with Nb S1 specific for human MSLN and Nb A1 that do cross-react with murine MSLN strongly suggest that the limited expression of MSLN on healthy tissues may not be a critical issue for clinical translation of Nb S1." (PMID 37388728, 2023). "Although concurrent administration of both CAR products did not increase the effectiveness of cancer-target anti-mesothelin CAR-T cells, neither did preconditioning the tumor microenvironment (TME) with FR-specific CAR-T cells." (PMID 37190310, 2023). "For example, many potential tumor biomarkers, including HE4 protein and serum mesothelin, were not included in the analysis." (PMID 37637510, 2023). "The CC tumor tissue and PSO exhibited negative expression of MSLN and MUC1 in the parenchymal region and positive expression of CD276." (PMID 38162496, 2023). "Although anti-mesothelin mouse CAR T cells show robust cytotoxicity against KPC cells in vitro, they show limited to no tumor control of KPC tumors in vivo." (PMID 36520915, 2022). "MSLN-CCR2b-CAR-T cells displayed superior anti-tumor function due to enhanced migration and infiltration into tumor tissues as well as no obvious toxicity (no organ damage)." (PMID 35211124, 2022). "In fact, a recent study shows that mesothelin is expressed in 93% of non-epithelioid MPM cases, confirming its over-expression in this rare tumor." (PMID 34199722, 2021). "There are many tumor markers on HCC cells that have not been yet targeted, such as EGFR, FGFR, PDGFR, MUC1, and mesothelin." (PMID 34679012, 2021). "Overall, 28 out of 43 patients (65%) whose tumours lacked a genomic match to a clinical trial were eligible for investigational drugs as a result of TMP analysis (PTEN, EGFR, HER2, GPNMB, MSLN, TROP2, TOPO1 or TOP2A as emerging positive predictive markers)." (PMID 31537838, 2019). "Mesothelin-positive and mesothelin-negative TNBC were not significantly different by patients’ race, tumor size, histologic grade, tumor subtype, lymphovascular invasion and lymph node metastases." (PMID 25506917, 2014). "However, for mice bearing MiaPaCa-2 tumors with low MSLN expression, CAR-like NK cell therapy did not significantly slow tumor growth or disease progression." (PMID 41436559, 2025).
tumor (continued). "Trying to bypass the sMSLN-related tumor resistance to CAR-T cells, Liu and colleagues built an anti-MSLN CAR-T (15B6 CAR-T) with an Ab recognizing an MSLN epitope close to the membrane that is not affected by MSLN shedding." (PMID 41335396, 2025). "Thus, MSLN expression is relatively uniform within stage II CRC tumors and high expression indicates a poorer prognosis, regardless of tumor area." (PMID 40227616, 2025). "The stability of BFP signal in Mesothelin- cells further underscores the targeted action of anti-Mesothelin CAR-NK-92 cells, confirming their potential efficacy in selectively targeting Mesothelin-expressing tumor cells while sparing non-expressing cells." (PMID 39781381, 2024). "The tumor tissue contained peptides from CA125 and mesothelin, but not HE4." (PMID 33413078, 2021). "Interestingly, however, host MSLN expression did not significantly impact proliferation, TIL infiltration, or macrophage infiltration in omental tumor tissues." (PMID 34830322, 2021). "Interestingly, this was not true when tumour volume on PET was added to the model, indicating that mesothelin was probably acting as a proxy for tumour bulk." (PMID 29454314, 2018). "Even though this finding suggested that sulfatase-1 could act as a tumor suppressor in HCC, caution should be exercised in interpreting it as no mesothelin expression was detected in human HCC specimen." (PMID 28218682, 2017). "Although lack of specificity of expression of mesothelin for mesothelial origin, the expression of this protein in DSRCT may have some significance on histogenisis of this tumor." (PMID 15777480, 2005). "However, due to the characteristics of solid tumors, such as the heterogeneity of tumor antigens, the inhibitory effect of the TME, and poor T-cell trafficking, the efficacy of anti-MSLN CAR-T cells in the treatment of MSLN-positive solid tumors is not satisfactory." (PMID 39023820, 2024). "However, even though important results were observed in preclinical studies, MSLN-CAR clinical trials showed low anti-tumor efficacy, possibly due to the heterogeneity of MSLN expression on tumor cells, as well as limited tumor penetration, or the lack of T cell persistence and exhaustion." (PMID 36831396, 2023). "However, even if the positivity rate of MSLN dropped to 90%, anti-MSLN CAR-T cells could not cure the tumor." (PMID 36900151, 2023). "Although target antigens are expressed on both tumor and normal cells, not all kinds of CAR-T cell therapies exhibit observable on-target, off-tumor toxicities, such as targeting carcinoembryonic antigen (CEA), mesothelin (MSLN), and Interleukin 13 receptor, Alpha2 (IL13Rα2)." (PMID 31783889, 2019). "Finally, because the effects of anti-CRD4 MR scFv #G11 on macrophage phenotype were more pronounced in the absence of tumor cells (condition 2), CD206 engagement by soluble mesothelin may compete with anti-CRD4-MR scFv binding." (PMID 22163010, 2011). "Furthermore, both the flow cytometry and immunofluorescence staining results confirmed that MSLN×CD16A could specifically bind to MSLN-positive tumor cells (MKN45, NCI-N87, HGC27, and CFPAC-1) but did not bind to MSLN-negative tumor cells (MiaPaCa-2 and HuH-7)." (PMID 41436559, 2025).
cancer (346 papers, 2006 to 2026). A tumor composed of atypical neoplastic, often pleomorphic cells that invade other tissues. "Then, we examined MSLN expression in other cancers associated with hepatotropic metastasis in several public datasets to broaden our findings." (PMID 41513618, 2026). "Given its overexpression in many cancer types, MSLN has been widely investigated as a potential diagnostic and prognostic biomarker for these malignancies." (PMID 41335396, 2025). "Mucin 16 (MUC16/CA125), which is expressed by PM cells and linked to the aggressiveness and progression of cancer, is known to bind to MSLN." (PMID 40227645, 2025). "MSLN’s function in facilitating cancer invasion has been demonstrated by its association with matrix metallopeptidase 9 (MMP-9) expression at the invasive margins of malignancies." (PMID 40227645, 2025). "Among the MSLN-overexpressing cancers, PM is the one with the greatest need for new diagnostic tools." (PMID 41335396, 2025). "MUC16/CA125 and mesothelin form a functionally important ligand-receptor pair that facilitates peritoneal adhesion and promotes invasive behavior in several cancers and their co-expression is associated with poorer prognosis and enhanced metastatic potential." (PMID 41515404, 2025). "Growing evidence supports mesothelin as a promising cancer-associated marker and a compelling target for CAR-T cell approaches in solid tumors." (PMID 40427042, 2025). "This double receptor construct is designed to treat genetically defined MSLN+ cancer patients with clonal LOH of the A*02 allele." (PMID 39023820, 2024). "Mesothelin (MSLN) is a cancer-associated antigen that is overexpressed on the membrane of cancer cells in several solid tumors including MM, especially in the epithelioid subtype." (PMID 38893092, 2024). "The tumor-associated antigen mesothelin is expressed at high levels on the cell surface of many human cancers, while its expression in normal tissues is limited." (PMID 36968141, 2023). "Mesothelin (MSLN) is a tumor-associated antigen foundin a varietyof cancers and is a target for imaging and therapeutic applicationsin MSLN-expressing tumors." (PMID 38027361, 2023). "This renders these highly treatment-resistant cancers susceptible to subsequent treatment with a tumor antigen (mesothelin)-targeted CAR T cells and to anti-PD-1 antibody therapy." (PMID 37607999, 2023). "Mesothelin is used both as a tissue marker and as a serum marker in association with CA-125 in several cancers." (PMID 37388728, 2023). "Over the years, evidence has accumulated with regards to the importance of MSLN as a tumor-associated antigen (TAA) overexpressed in almost one-third of human cancers." (PMID 35795680, 2022). "It is almost certain that the use of different antibodies, protocols, and interpretation criteria have jointly caused highly diverse literature data on MSLN expression in cancer." (PMID 33917081, 2021). "Upregulation of MSLN in adult humans is associated with cancer, and was recently linked to the development of cholestatic fibrosis." (PMID 34966784, 2021). "This is in line with data from 4 earlier studies all describing associations between high MSLN expression and parameters for cancer aggressiveness or poor patient prognosis." (PMID 33917081, 2021). "Using the example of MSLN in PDAC, we demonstrate how the method identifies potentially interacting genes and pathways associated with MSLN within the cancer cell in its native microenvironment." (PMID 32616712, 2020). "Mesothelin (MSLN) is a lineage restricted cell surface protein expressed in about 30% of human cancers and high MSLN expression is associated with poor survival in several different cancers." (PMID 33262421, 2020). "Mesothelin (MSLN) is a cell surface glycoprotein that is normally expressed in the mesothelial cells but highly expressed in several malignant tumors, where the high expression is generally associated with poor prognosis." (PMID 33196692, 2020).